PDLIM3 (PDZ and LIM domain 3)
Diseases named in the same sentence as PDLIM3 in open-access papers (continued):
Sharing a sentence is not in itself a finding about the gene and the disease.
prostate carcinoma (2 papers, 2022 to 2025). A carcinoma that arises from epithelial cells of the prostate gland. "Estrogen stimulation increases the expression of PDLIM3 in human prostate cancer." (PMID 36339397, 2022).
tongue cancer (2 papers, 2025). A malignant neoplasm affecting the tongue. "They found elevated PDLIM3 expression in tongue cancer with early regional lymph node metastasis." (PMID 40243891, 2025).
colitis (1 paper, 2025). Inflammation of the colon. "Our study reveals that KS exposure promotes colitis via the gut microbiota and PDLIM3 interaction, providing evidence of IBD pathogenesis and a potential therapeutic strategy for IBD treatment." (PMID 41287530, 2025). "Furthermore, tubuloside B, which is selected by high-throughput screening, blocks the interaction of PDLIM3 and LPDP, and ameliorates SL-aggravated colitis." (PMID 41287530, 2025).
dilated cardiomyopathy (1 paper, 2019). "A PDLIM3 or PDLIM5 deficiency in mice leads to dilated cardiomyopathy." (PMID 31424159, 2019).
gastric tumors (1 paper, 2022). "In the HPA database, PDLIM3 protein expression and antibody staining levels in gastric tumors were moderate, while nontumor tissues were negative." (PMID 35647201, 2022). "As expected, the results revealed that the average IOD of PDLIM3 immunostaining in gastric tumors (41.7 ± 16.5) was significantly stronger than in matched nontumor samples (19.5 ± 10.8) (P < 0.001)." (PMID 35647201, 2022). "We also quantified PDLIM3 expression in 15 matched pairs of gastric tumor and nontumor tissues by immunohistochemistry." (PMID 35647201, 2022).
glioblastoma (1 paper, 2025). The most malignant astrocytic tumor (WHO grade IV). "This research provides the first evidence that PDLIM3 may contribute to the aggressiveness of glioblastoma by facilitating GSCs sphere formation and enhancing their invasiveness." (PMID 40704301, 2025). "In order to evaluate the prognostic significance of PDLIM3 in glioblastoma (GBM), we created Kaplan-Meier survival analysis curves utilizing PDLIM3 expression data sourced from the different databases." (PMID 40704301, 2025).
heart hypertrophy (1 paper, 2022). "Considering its co-localisation with Pdlim3, CPXM2 could potentially be involved in Pdlim3-mediated effects during the development of heart hypertrophy and fibrosis." (PMID 35216380, 2022).
hepatocellular carcinoma (1 paper, 2021). A malignant tumor that arises from hepatocytes. "Eventually, we found that CYP7A1/GINS2/PDLIM3 were associated with the prognosis of hepatocellular carcinoma (HCC) in the TCGA database." (PMID 34777484, 2021).
liver cancer (1 paper, 2022). An epithelial or non-epithelial malignant neoplasm that arises from the liver. "We first compared PDLIM3 expression in different carcinomas and nontumor tissues via Oncomine data, finding that relative to nontumor tissues, PDLIM3 expression was elevated in esophageal, brain and CNS, kidney, gastric, pancreatic, liver cancer, lymphoma, and sarcoma." (PMID 35647201, 2022).
lung carcinoma (1 paper, 2014). "This analysis resulted in 4 novel miR-21 putative target genes; solute carrier family 5 (iodide transporter) member 8 (Slc5a8), lipopolysaccharide binding protein (Lbp), V-myc myelocytomatosis viral oncogene homolog 1, lung carcinoma derived (Mycl1), PDZ and LIM domain 3 (Pdlim3)." (PMID 24497923, 2014).
metastatic tumors (1 paper, 2022). "Interestingly, we found that CTHRC1, NTM, PDGFC, PDLIM3, and SLC16A3 are gradually upregulated from normal to a metastatic tumor, indicating the association of these genes in tumor progression (Welch’s t-test, p < 0.05)." (PMID 35991839, 2022). "Moreover, the CTHRC1, PDGFC, PDLIM3, NTM, and SLC16A3 genes are gradually increased from normal tissue to the tumor and tumor to the metastatic tumor, and FBN2 showed the reverse pattern." (PMID 35991839, 2022).
muscular dystrophy (1 paper, 2020). Muscular dystrophy (MD) refers to a group of more than 30 genetic diseases characterized by progressive weakness and degeneration of the skeletal muscles that control movement. "Similarly, PDLIM3 was also associated with both DCM and muscular dystrophy, in the form of myotonic dystrophy." (PMID 32013268, 2020).
pancreatic cancer (1 paper, 2025). "A role of PDLIM3 has also been reported in tumorigenesis and metastatic potential of pancreatic cancer, with a decrease in the migratory properties of pancreatic cancer cells when its expression is downregulated." (PMID 40704301, 2025).
papillary thyroid carcinoma (1 paper, 2023). "PDLIM3 expression was also decreased in papillary thyroid carcinoma (PTC) samples from the Chernobyl region, but the correlation between PDLIM3 expression and clinical stage, metastasis, and prognosis of thyroid carcinoma (THCA) patients and its role in the pathogenesis of THCA is unclear." (PMID 37894409, 2023).
steatosis (1 paper, 2021). Increased lipid within the cytoplasm of cells. "Eventually, we determined 10 hub genes (Down-regulated genes: MYC, TGFB3, ADAMTS1, THBS1, RASD1, PCDH20; Up-regulated genes: MAMDC4, CYP7A1, GINS2, and PDLIM3) related to NAS and steatosis." (PMID 34777484, 2021).
Stroke (1 paper, 2025). Sudden impairment of blood flow to a part of the brain due to occlusion or rupture of an artery to the brain. "Nine days post-stroke, proteins annotated as thin filaments were upregulated, including Ablim1, Dbnl, Parvb, Capg, and Pdlim3; Actn2, Pdlim7, Tpm1, and cofilin 2 (Cfl2) were downregulated." (PMID 41226396, 2025). "Six days post-stroke, differentially expressed thin filament proteins were annotated as follows: Ablim1, Pdlim1, Lmod2, Dbnl, Parvb, Pdlim3, Tpm2, parvin alpha (Parva), and destrin (Dstn) were upregulated, while Lmod3 was downregulated." (PMID 41226396, 2025).
tumor (13 papers, 2012 to 2025). "The dysregulation of PDZ and LIM domain protein 3 (PDLIM3) in pan–cancer indicates its significance in tumor progression." (PMID 40243891, 2025). "An analysis of a public dataset containing information on tumor metastasis in HNSCC patients (GSE188737) revealed that PDLIM3 was significantly downregulated in patients with metastasis." (PMID 40243891, 2025). "Down-regulated Pdlim3 is critical for sonic hedgehog signal transduction, as its elimination represses the tumor growth and metastasis." (PMID 40006055, 2025). "Our study aims to evaluate its biological contribution and clinical value in tumor progression by analyzing the expression levels of PDLIM3 in HNSCC." (PMID 40243891, 2025). "For PDLIM3, the results of IHC in the stroma are comparable to those of MS, and its abundant responses to CP in IHC in the tumour are different from its signals gained from MS PDLIM3 increases in CP‐s in IHC but no change in MS." (PMID 40697100, 2025). "Then, the expression of PDLIM3 in paired samples of HNSCC and normal tissue was compared, and PDLIM3 expression was significantly downregulated in the tumor." (PMID 40243891, 2025). "Here, we compared the PDLIM3 mRNA expression levels between non-tumor brain samples and GBM samples from TCGA and Rembrandt databases." (PMID 40704301, 2025). "TFRC and ALDH5A1 were located in the tumour, PDLIM3 in the stroma, and CA1 and APM2 in both regions." (PMID 40697100, 2025). "Investigating the implications of PDLIM3 for tumor metastatic ability in vitro, we found that PDLIM3 suppressed the migration and invasion of HNSCC, accompanied by partially impeding the process of epithelial–mesenchymal transition (EMT)." (PMID 40243891, 2025). "The expression levels of PDLIM3 were analyzed using public datasets to assess its potential role in tumor progression." (PMID 40243891, 2025). "More clearly demonstrating its potential to regulate tumor immunity, marked positive correlations were found between PDLIM3 and specific immunological markers." (PMID 35647201, 2022). "We also used immunohistochemical staining to evaluate PDLIM3 in high-stroma tumors quantified in H-E slides as the tumor/stroma ratio." (PMID 25115384, 2014). "To achieve this, we examined PDLIM3 expression in relation to tumor grade." (PMID 40704301, 2025). "Furthermore, our findings suggest that PDLIM3 acts as a tumor suppressor in HNSCC by inhibiting migration and invasion." (PMID 40243891, 2025). "Our findings identify a potential signaling axis wherein PDLIM3 regulates YAP–EMT, thereby influencing tumor metastatic ability, and suggest the potential role of PDLIM3 as a tumor suppressor and prognostic biomarker for HNSCC." (PMID 40243891, 2025). "Our findings reveal that PDLIM3, which is significantly downregulated in HNSCC, functions as a potential tumor suppressor by inhibiting migration, invasion, and epithelial–mesenchymal transition (EMT)." (PMID 40243891, 2025). "Specifically, in the staining images of the tumour and stroma regions, ALDH5A1, TFRC, and PDLIM3 showed different staining intensities between the two regions, whereas APM2 exhibited poor recognition in differentiating tumour from stroma." (PMID 40697100, 2025). "Beyond PDLIM3, other PDLIM family proteins have similar functions and participate in tumor progression." (PMID 40243891, 2025). "We found that the RNA expression levels of PDLIM3, PAM, PDLIM7, FSCN1 and LGALS3 were significantly upregulated in tumor samples, which provides ideas for further studies." (PMID 36177006, 2022). "We found that CYP7A1, GINS2, and PDLIM3 were significantly up-regulated, and MYC, MAMDC4, ADAMTS1, THBS1, and RASD1 were significantly down-regulated in HCC tumor samples compared with normal samples using the TCGA dataset." (PMID 34777484, 2021). "We found that CYP7A1, GINS2, and PDLIM3 were significantly up-regulated, and MYC, MAMDC4, ADAMTS1, THBS1, and RASD1 were significantly down-regulated in HCC tumor samples compared to normal samples." (PMID 34777484, 2021).
tumor (continued). "PDLIM3 was significantly upregulated in the stroma of CP‐s, but no change was observed between CP‐i and CP‐s in the tumour, and CA1 and APM2 remained in a similar mode of abundance changes in the tumour and stroma between CP‐i and CP‐s groups." (PMID 40697100, 2025). "Notably, about 45% of the tumor samples were PDLIM3–negative, while PDLIM3 expression was detected in all normal samples." (PMID 40243891, 2025). "Further examination of the IHC signals in the tumour and stroma between CP‐i and CP‐s revealed that TFRC and PDLIM3 displayed significantly increased abundance in CP‐s, but not in CP‐i, and ALDH5A1 and APM showed no significant changes between CP‐i and CP‐s." (PMID 40697100, 2025).
cancer (7 papers, 2016 to 2025). A tumor composed of atypical neoplastic, often pleomorphic cells that invade other tissues. "Furthermore, PDLIM3 has been shown to be associated with the immune response in cancer." (PMID 40704301, 2025). "Dysregulation of PDLIM3 in pan–cancer is primarily characterized by altered mRNA levels, with limited genetic alterations." (PMID 40243891, 2025). "The inconsistent expression patterns of PDLIM3 highlight the complexity of its regulatory mechanisms in cancers." (PMID 40243891, 2025). "Taken together, our results indicate that PDLIM3 is widely downregulated in pan–cancer, and the downregulation of PDLIM3 in HNSCC correlated with poor patient prognosis." (PMID 40243891, 2025). "Oncomine data were also utilized to summarize the expression of PDLIM3 in several types of cancers (for detailed results)." (PMID 35647201, 2022). "On the other hand, epigenetic mechanisms or specific microRNA regulation may contribute to the distinct expression patterns of PDLIM3 across different cancers." (PMID 40243891, 2025). "We found that PDLIM3 was downregulated in pan–cancer and HNSCC." (PMID 40243891, 2025). "Moreover, the expression of PDLIM3 in multiple carcinomas from the TCGA database was summarized using the GEPIA database." (PMID 35647201, 2022). "However, recent research has revealed aberrant expression of PDLIM3 in various cancers." (PMID 40243891, 2025). "Notably, mRNA levels are significantly downregulated in pan–cancer (32.9%), indicating that PDLIM3 may play a crucial role in tumorigenesis and development." (PMID 40243891, 2025). "Thus, PDLIM3 might be a predictor of cancer progression, invasion, and metastasis." (PMID 35647201, 2022). "Other genes whose protein products have evidence of function in cancer include RCN3, RRBP1, PDLIM3 and SLC1A4." (PMID 27689402, 2016).
myopathy (3 papers, 2023 to 2025). A disease of the muscle in which the muscle fibers do not function properly. "Interestingly, all of these genes are associated with genetic (cardio)myopathies in humans (TTN, NEB, MYBPC1, TNNT3 and TPM1) or mice (PDLIM3)." (PMID 37000196, 2023).
cardiac disease (2 papers, 2020 to 2022). "The protein product of PDLIM3 is predicted to interact with the protein products of several other genes that are linked with heart disease, including MYBPC3, ACTN2, and CAV3." (PMID 32013268, 2020).
PDLIM3 also shares sentences with these, for which no sentence is quoted: bladder cancer (1 paper); cardiac arrhythmia (1); cystadenoma (1); head and neck squamous cell carcinoma (1); heart failure (1); invasive bladder urothelial carcinoma (1); lymphoma (1); myotonic dystrophy (1); myotonic dystrophy type 1 (1); ovarian endometriosis (1); renal cell carcinoma (1); rhabdomyosarcoma (1); sarcoma (1); thyroid carcinoma (1).